NRAS (NRAS proto-oncogene, GTPase)
Diseases named in the same sentence as NRAS in open-access papers (continued):
Sharing a sentence is not in itself a finding about the gene and the disease.
melanocytic nevus (5 papers, 2016 to 2024). A neoplasm composed of melanocytes that usually appears as a dark spot on the skin. "The other case, harboring a singular NRAS mutation (G12/G13), occurred on the trunk of a 33-year-old female and was classified as a mixed melanocytic nevus." (PMID 38396984, 2024). "In this context, it is also interesting to note that melanocytic naevi with mutations in the NRAS signalling pathway (NRAS or BRAF mutations) require additional driver mutations to avoid senescence, e.g., in the CDKN2A locus." (PMID 33138083, 2020). "Instead of GNAQ or GNA11 mutations, these patients frequently demonstrate identical NRAS mutations in both the congenital melanocytic nevus and in the LMN." (PMID 26769193, 2016).
plasma cell dyscrasia (5 papers, 2017 to 2023). "From a cohort of 217 patients with plasma cell neoplasm that underwent NGS mutation profiling, we identified 68 (31.3%) patients who had mutations in RAS signaling pathway genes (KRAS, NRAS or BRAF) and no other mutations." (PMID 37212518, 2023).
Splenomegaly (5 papers, 2016 to 2024). Abnormal increased size of the spleen. "In addition, as expected, myeloproliferative features such as CMML-MP variant, leukocyte count or presence of splenomegaly, correlated with genes involved in cell signaling, such as NRAS and JAK2." (PMID 27486981, 2016). "For example, somatic mutation in NRAS or KRAS genes in hematopoietic cells can cause a rare autoimmune disorder, characterized by lymphadenopathy and splenomegaly due to abnormal expansion of lymphocytes." (PMID 28736556, 2017). "Mutations in NRAS correlated with FAB CMML-MP subtype/leukocyte count (P=0.015), presence of splenomegaly (P>0.001) and age <70 years (P=0.012)." (PMID 27486981, 2016).
squamous cell carcinoma (5 papers, 2009 to 2025). A carcinoma arising from squamous epithelial cells. "Less common mutations, such as NRAS and PIK3CA, also warrant additional investigation in adenocarcinoma and squamous cell carcinoma, potentially through targeted clinical trials." (PMID 40502411, 2025). "These included 12 adenocarcinomas, 9 squamous cell carcinomas and 1 large cell carcinoma, all examined for known EGFR/KRAS/NRAS/HRAS/PI3K mutations." (PMID 19806209, 2009).
thyroid (5 papers, 2015 to 2025). "Taking NRAS and HRAS for instance, they are members of oncogenic RAS and the clinical impact of RAS mutations on the management of thyroid nodules with indeterminate cytology is unsatisfactory." (PMID 36137089, 2022). "The objective of the study was to determine if the analysis of mutations (BRAF, NRAS, KRAS and HRAS) using readily available molecular techniques can help better classify indeterminate thyroid nodules." (PMID 26621130, 2015). "Our analysis, however, highlights substantial differences in DNAm between BRAF-mutated vs. NRAS- and HRAS-mutated THCA tumors; moreover, the differences in DNAm appear to profoundly shape gene expression profiles, which may contribute to thyroid tumorigenesis." (PMID 29125844, 2017).
follicular adenoma (4 papers, 2019 to 2025). "The low number of NRAS mutations particularly resulted from the few cases of follicular papillary carcinoma (24%) and follicular adenoma (2%) which commonly harbor NRAS mutation." (PMID 33247684, 2020).
head and neck cancer (4 papers, 2018 to 2021). A primary or metastatic malignant neoplasm affecting the head and neck. "Activating mutations in one of the three RAS genes (HRAS, KRAS, and NRAS) are observed in 5–10% of patients with head and neck cancer, and HRAS mutations in particular are detected in > 50% of patients with head and neck cancer." (PMID 29374236, 2018).
lentigo maligna melanoma (4 papers, 2022 to 2025). A skin cancer that usually develops in older, fair-skinned adults. "Considering NRAS-mutated cases, the most prevalent subtypes were SSM (5/23, 22%), and lentigo maligna melanoma (3/23, 13%)." (PMID 39000050, 2024).
meningioma (4 papers, 2020 to 2025). A generally slow growing tumor attached to the dura mater. "- Meningiomas: WT1- Hemangiomas: VEGFR2, Endoglin (CD105)- Melanocytic nevi: MART-1, BRAF, NRAS mutations- Lipoma: HMGA2-expressing cells." (PMID 40630962, 2025).
ovarian tumor (4 papers, 2018 to 2026). "As for genetic alterations characteristic of less aggressive ovarian tumors, the genes with the highest number of polymorphisms in BOTS and lgOvCa compared to hgOvCa were KRAS, BRAF, and NRAS, which is in line with the scientific literature." (PMID 39456660, 2024). "Certain mutations seem to play an important role in BOTS without the BRAF V600E variant (KRAS) and in lgOvCa (KRAS and NRAS), but not in hgOvCa, once again proving that advanced OvCa are molecularly distinct from less aggressive ovarian neoplasms." (PMID 39456660, 2024).
plasma cell leukemia (4 papers, 2018 to 2024). An aggressive plasma cell neoplasm characterized by the presence of neoplastic plasma cells in the peripheral blood. "According to published data, mutations of RAS family genes (KRAS, NRAS, BRAF) occur in less than 10% in MGUS, in 50% of symptomatic MM, and in more than 70% of cases of plasma-cell leukemia, which indicates activation of this pathway in the progression of the disease." (PMID 36833278, 2023).
plasmacytoma (4 papers, 2022 to 2025). Plasmacytoma is a localized mass of neoplastic monoclonal plasma cells that represents approximately 5% of all plasma cell neoplasms. "KRAS gene mutation was detected in seven patients (in six bone marrow samples and one plasmacytoma sample), and NRAS gene mutation was detected in six patients (in five bone marrow samples and one plasmacytoma sample)." (PMID 36833278, 2023). "Notably, all these rare KRAS and NRAS gene mutations were found only in the group of patients with plasmacytoma." (PMID 40943426, 2025). "In the 11 extramedullary plasmacytomas, mutations were detected in the NRAS gene in 27% of cases (n = 3) and in the BRAF gene in 18% (n = 2), suggesting a tendency for KRAS mutations to be more frequent in bone lesions, while NRAS mutations were more common in extramedullary sites." (PMID 40943426, 2025). "We have measured KRAS, NRAS, and BRAF gene mutations in circulating free tumor DNA (ctDNA) from plasma, bone marrow, and plasmacytoma samples as well as their correlation with various clinical and laboratory parameters." (PMID 40943426, 2025). "Mutations in the KRAS, NRAS, and BRAF genes either in bone marrow, ctDNA, or plasmacytoma samples were found in 50% of patients." (PMID 40943426, 2025). "The frequency of the KRAS, NRAS, and BRAF gene mutations in any of the tumor substrate (bone marrow, ctDNA, plasmacytoma) in the entire group was 50% (56 out of 113)." (PMID 40943426, 2025). "Here, we present an analysis of the STR profiles and mutation status of the KRAS, NRAS, and BRAF genes, evaluated in plasma free circulating tumor DNA (ctDNA), CD138+ bone marrow cells, and plasmacytomas." (PMID 39273371, 2024). "In Patient 24, the NRAS gene was mutated in the plasmacytoma substrate, but no mutation of this gene was detected in the bone marrow and ctDNA." (PMID 40943426, 2025). "The NRAS gene, a mutation of which has been detected in a retroperitoneal plasmacytoma, but not in bone marrow or plasma ctDNA, is located on chromosome 1 in the 1p13.2 region." (PMID 40943426, 2025). "In two patients, there was a mutation in the KRAS or NRAS gene in plasmacytoma tissue, while the corresponding gene was not mutated in bone marrow or ctDNA." (PMID 39273371, 2024). "NRAS or KRAS genes were mutated in plasmacytomas, while in the bone marrow or plasma ctDNA the genes were not affected." (PMID 36833278, 2023). "The presence of mutations in the KRAS, NRAS, and BRAF genes is more prevalent in the ctDNA of patients with plasmacytoma compared to those without." (PMID 40943426, 2025). "A principal finding of this work is that mutations in KRAS, NRAS, or BRAF genes within ctDNA were significantly more prevalent in patients with plasmacytoma compared to those without (28% vs. 0, p = 0.0007)." (PMID 40943426, 2025).
rectal tumors (4 papers, 2020 to 2025). "A study in the United States reported that NRAS mutations were associated with rectal tumors and BRAF mutations to old age in agreement with our findings." (PMID 32628708, 2020). "A tendency was found in the Japanese population where mutations in KRAS or NRAS were more common in rectal tumors, while our analysis showed a tendency in the proximal colon for KRAS-mutated and rectal tumors for NRAS-mutated." (PMID 32628708, 2020). "Rectal tumors exhibit distinctive biological characteristics when compared to left-sided tumors, including a higher absence rate of KRAS, NRAS, and BRAF mutations (47.4% in rectal versus 42.8% in left-sided tumors)." (PMID 38409377, 2024).
salivary gland tumors (4 papers, 2015 to 2024). "PIK3CA mutations were found in 59% of HRAS-mutant salivary gland tumors but due to the limited number of KRAS- and NRAS-mutant tumors of this lineage this was not significantly different, but was more prevalent than in other HRAS-mutant cancers (p<0.05)." (PMID 37503077, 2023).
Thrombocytopenia (4 papers, 2022 to 2024). A reduction in the number of circulating thrombocytes. "Although some features were potentially non-specific, oncogene expression was restricted to the HSPC compartment, and phenotypes are consistent with murine leukaemia models where oncogenic NRAS expression leads to symptomatic anaemia and thrombocytopaenia." (PMID 39177514, 2024). "One somatic NRAS mutant patient also continues in active surveillance at 90 months after diagnosis with stable thrombocytopenia, thus not meeting remission criteria." (PMID 39123476, 2024).
thymic carcinoma (4 papers, 2017 to 2025). Thymic carcinoma (TC) is a type of thymic epithelial neoplasm characterized by a high malignant potential. "The receptor tyrosine kinases ALK and ERBB4, the serine/threonine kinase ATM, and the GTPase NRAS were mutated in one thymic carcinoma each." (PMID 27844328, 2017).
acute T-cell lymphoblastic leukemia (3 papers, 2012 to 2022). "Several pairs of co-occurring mutations were found: NRAS with SETD, NRAS with PTPN11 in B-cell ALL (p = 0.024 and p = 0.020, respectively), and NOTCH1 with FBXW7 in T-cell ALL (p < 0.001)." (PMID 36362526, 2022).
astrocytomas (3 papers, 2021 to 2023).
Autoimmunity (3 papers, 2017 to 2024). The occurrence of an immune reaction against the organism's own cells or tissues. "Somatic mutation in NRAS or KRAS may cause a rare autoimmune disorder coupled with abnormal expansion of lymphocytes." (PMID 28736556, 2017). "All PRKCD, CTLA4, TET2 and NRAS/KRAS patients presented clinically with lymphoproliferation and autoimmunity, considering all those reported cases (n=197) as ALPS-like patients." (PMID 34447369, 2021). "However, only 100% of CTLA4, PRKCD, TET2 and NRAS/KRAS reported patients had an ALPS-like presentation, while the autoimmunity and lymphoproliferation combination resulted rare in other genetic defects." (PMID 34447369, 2021).
breast tumors (3 papers, 2012 to 2022). "The data showed that the top hallmark pathways induced after NRAS overexpression are enriched with immune/inflammatory pathways, which is similar to what has been reported previously in basal-like breast tumors." (PMID 36258226, 2022). "Although there was not a substantial change in KRAS mRNA, Paranjape and colleagues reported an enrichment of both NRAS mutant and MAPK activation signatures in breast tumors that had the KRAS variant." (PMID 22436609, 2012).
chondrosarcoma (3 papers, 2017 to 2024). A malignant cartilaginous matrix-producing mesenchymal neoplasm arising from the bone and soft tissue.
COVID-19 (3 papers, 2021 to 2024). A disease caused by infection with severe acute respiratory syndrome coronavirus 2. "In conclusion, our study provides global insights into the transcriptome profiles of host responses in COVID-19-vaccinated individuals and identifies MAPK1, CDC42, PPP2CA, EP300, YWHAZ and NRAS as hub genes that are significantly correlated with the vaccine response." (PMID 37096063, 2023).
Cutaneous T-cell lymphomas (3 papers, 2016 to 2021). "Cutaneous T-cell lymphomas (CTCLs) make up about 4% of non-Hodgkin lymphomas and the NRAS Q61K mutation in Hut78 cells has been determined as a significant oncogenic factor in CTCL development." (PMID 33801781, 2021). "Therapy of cutaneous T cell lymphoma (CTCL) is complicated by a distinct resistance of the malignant T cells towards apoptosis that can be caused by NRAS mutations in late-stage patients." (PMID 28537899, 2017).
dysplastic nevi (3 papers, 2009 to 2024). "Presence of BRAF mutations in benign and dysplastic nevi supports the hypothesis that activation of the NRAS-BRAF-ERK pathway is not sufficient to induce the malignant process and fully transform proliferating melanocytes, but requires additional, cooperating de-regulative events." (PMID 19799798, 2009).
hepatoblastoma (3 papers, 2019 to 2022). Hepatoblastoma (HB) is a malignant hepatic tumor and is the most common pediatric liver cancer. "These issues should be avoided as much as possible in future studies to better investigate the relationship between hepatoblastoma risk and NRAS and KRAS polymorphisms." (PMID 31086727, 2019). "HepG2, derived from an hepatoblastoma, displays 299 mutations and CNAs including CTNNB1 exon 3 deletion and NRAS missense mutation." (PMID 32515546, 2020). "We find that NRAS and KRAS polymorphisms are irrelevant to hepatoblastoma susceptibility among Chinese population." (PMID 31086727, 2019). "The data suggest that NRAS and KRAS polymorphisms are irrelevant to hepatoblastoma susceptibility among Chinese population." (PMID 31086727, 2019). "In this study, we analyzed the association between NRAS and KRAS polymorphisms and hepatoblastoma risk." (PMID 31086727, 2019).
histiocytic sarcoma (3 papers, 2023 to 2025). An aggressive malignant neoplasm with a poor response to therapy, usually presenting as stage III/IV disease. "One patient had concomitant KRAS p.A59E mutated histiocytic sarcoma and CMML, one patient had synchronous NRAS p.G12V mutated indeterminate cell histiocytosis and CMML and finally, one patient had subsequent NRAS p.Q61R mutated ECD and AML." (PMID 38136431, 2023). "On a molecular basis, alterations affecting the RAS/RAF/MAPK signaling cascade - such as KRAS, NRAS, BRAF, and others - are commonly reported in histiocytic sarcoma." (PMID 40901224, 2025).
Immunodeficiency (3 papers, 2020 to 2025). Failure of the immune system to protect the body adequately from infection, due to the absence or insufficiency of some component process or substance. "On the other hand, NRAS and HRAS appear less crucial; NRAS and HRAS knockout mice exhibited normal phenotypes and moderate immunodeficiency, respectively, indicating that these genes are not as widely expressed." (PMID 39857784, 2025).
inflammatory bowel disease (3 papers, 2024 to 2025). A spectrum of small and large bowel inflammatory diseases of unknown etiology. "Our patient’s case illustrates this sporadic pattern well, as he had no family history of cancer, he tested negative for KRAS, NRAS, BRAF, and PIK3CA mutations, and he showed no signs of inflammatory bowel disease." (PMID 41487588, 2025).
Langerhans cell histiocytosis (3 papers, 2019 to 2024). Langerhans cell histiocytosis (LCH) is a systemic disease associated with the proliferation and accumulation (usually in granulomas) of Langerhans cells in various tissues. "Non-Langerhans cell histiocytosis shares a high incidence similar to that of BRAF V600E mutations, along with genetic alterations in ARAF, MAP2K1, PIK3CA, K/NRAS, and gene fusions involving BRAF, ALK, NTRK1, and ETV3-NCOA2." (PMID 38963520, 2024). "Somatic NRAS c.182A > G (p.Q61R) mutations have also been identified in nonmalignant cancers, including pyogenic granuloma and Langerhans cell histiocytosis." (PMID 31511039, 2019). "PCR results showed that there were no BRAF-V600E, KRAS, or NRAS mutations in primary intraosseous RDD; only one case with both RDD and Langerhans cell histiocytosis showed BRAF-V600E mutation." (PMID 36185213, 2022).
Lewis lung carcinoma (3 papers, 2017 to 2023). "Indeed, treating either KRASG12C-expressing MEFs or the established Lewis lung carcinoma cell line (3LL) - in which NRAS was knocked out (deltaNRAS86) leaving them only with an activating point mutation in KRASG12C - with the KRASG12C inhibitor AMG510 sensitized these cells to ferroptosis." (PMID 36443441, 2023).
lung squamous cell carcinoma (3 papers, 2017 to 2024). "Our results suggest that it is most likely to indicate the occurrence of NRAS, AKT1 and PTEN mutations in metastatic sites of squamous cell lung carcinoma." (PMID 28097440, 2017). "Notably, the ubiquitome analysis of the Clinical Proteomic Tumor Analysis Consortium (CPTAC) lung squamous cell carcinoma (LUSC) dataset revealed that lung tumor samples presented decreased levels of NRAS and KRAS ubiquitination at K128 in comparison to normal tissue." (PMID 38858602, 2024).